CDK4 (cyclin dependent kinase 4)
Diseases named in the same sentence as CDK4 in open-access papers (continued):
Sharing a sentence is not in itself a finding about the gene and the disease.
tumor (continued). "This combination, particularly when a cycle of FMD was added to a regimen of fulvestrant and palbociclib (a CDK4/6 inhibitor), not only induced durable tumor regression but also countered the development of acquired resistance to the medications." (PMID 38321992, 2024). "The frequent genomic alterations in CDKN2A and CCND1 in HPV− clinical HNSCC cases suggest that there is a strong rationale to target CDK4/6 to inhibit tumor progression in HNSCC." (PMID 38954773, 2024). "Inhibition of the CDK4/6 activity is also beneficial for tumor cells that lack the Rb protein, leading to apoptosis or a delay of the G1/S transition." (PMID 39598723, 2024). "In those tumours, combined inhibition of CDK4/6 and signalling pathways upstream of CDK4 activation (MAPK and/or PI3K‐mTOR) is required to fully and durably suppress their proliferation." (PMID 36453028, 2024). "Blocking EZH2 in orthotopic, murine, KPC tumors, treated with MEK and CDK4/6 inhibitors, subsequently led to an increase in intra-tumoral CCL2 and CXCL9/10 production and was associated with NK- and T-cell influx and anti-tumor responses." (PMID 38339310, 2024). "•Preventive CDK4/6 inhibition with abemaciclib significantly delays tumor development in preclinical hereditary cancer models." (PMID 38986222, 2024). "The combination of CDK4/6 inhibitors with other targeted therapies additionally promotes tumour immunity by enhancing cellular senescence in tumour cells." (PMID 39270064, 2024). "For instance, several preclinical studies have indicated that CDK4/6i can boost tumor cell immunogenicity, leading to the exploration of CDK4/6i and Immune checkpoint inhibitor (ICI) combinations." (PMID 38409585, 2024). "The CDKN2A gene is a tumor suppressor gene that binds and inactivates cyclin-dependent kinase 4 and 6, thus impeding phosphorylation of various growth and regulation factors which control proliferation." (PMID 38607041, 2024). "The combination of CDK4/6 inhibitors with immune checkpoint blockade improves the effect of tumor immunotherapy." (PMID 39461947, 2024). "The most interesting point of this study is that CDK4/6i‐induced senescence still maintains the expression of SASP and ligands associated with anti‐tumor immunity." (PMID 37854019, 2024). "Additional studies highlighted an importance of cyclin D1 levels in resistance of cancer cells to PI3Kα inhibitors and revealed a synergistic anti-tumor effect upon combined targeting with CDK4/6 inhibitors." (PMID 38286037, 2024). "More excitingly, combining CDK4/6 inhibitor with anti-PD-1 immunotherapy promotes tumor regression and significantly increases overall survival in mouse tumor models." (PMID 38605349, 2024). "By inhibiting CDK4 activity, involucrasin B can impede the proliferation and division of cancer cells, thereby restraining tumor progression." (PMID 38338430, 2024). "Other attempts with metal-based PET tracers entrapped in chelators extended from the piperazine moiety of CDK4/6 inhibitors led to abysmal tumor uptake." (PMID 38999983, 2024). "Similar to the data obtained from cell lines, HZ1 markedly decreased the levels of pRb and CDK4, hence effectively triggering cell cycle arrest and tumor death." (PMID 38963708, 2024). "This strategy, in tandem with palbociclib, a recognised CDK4/6 inhibitor with anti‐cancer effects, enhances the therapeutic approach to tumour treatment." (PMID 39270064, 2024). "We showed before that the combination of XVir-N-31 and CDK4/6 inhibition (CDK4/6i) has the capacity to jointly activate innate and adaptive immunity in EwS with superior tumor control and signs of an abscopal effect." (PMID 38318175, 2024).
tumor (continued). "P16 functions as a tumor suppressor, acting through CDK4 and CDK6 to keep the retinoblastoma (Rb) gene product hypophosphorylated, hence inactivated, pausing the cell cycle." (PMID 38989391, 2024). "Co-overexpression of both CCND1 and CDK4 is common in hepatoblastoma, a rare malignant liver tumor of childhood, and usually positively correlated with tumor recurrence." (PMID 36839989, 2023). "On this basis, PARPi and CDK4/6 inhibitor combinations are currently under evaluation including in MYC amplified tumours (NCT04693468)." (PMID 37430137, 2023). "Tumor tissues from CDK4/6i monotherapy showed higher protein levels of LRPPRC and CDK6 compared to the control group, indicating the activation of the LRPPRC-CDK6 feedback loop after CDK4/6i treatment in vivo." (PMID 37452037, 2023). "Optimal sequencing post-CDK4/6i should be personalized to the patient’s functional status and tumor biology." (PMID 36980743, 2023). "The fact that patients with tumor expression of CDK4 above the median value showed a longer PFS and OS would suggest there is a margin for improvement in the CDK4 cutoff." (PMID 37875500, 2023). "The best characterized mechanism by which CDK4/6 inhibitors act is the inhibition of retinoblastoma protein (Rb) phosphorylation, leading to G1 cell cycle arrest in tumor cells." (PMID 37035239, 2023). "A combination of SCR-6852 and a CDK4/6 inhibitor revealed synergistically anti-tumor activities both in vitro and in vivo." (PMID 37580832, 2023). "In order to find out which gene is more critical in Cdk4−/− medicated anti-tumor responses, Cdk4−/−/Sting−/− and Cdk4−/−/Mavs−/− MCA205 cell lines were established by CRISPR/Cas9 technology with specific sg-RNA pairs." (PMID 37833461, 2023). "As such, knockdown of FOXM1 increases the expression of p16INK4a and other CDK inhibitors, whereas FOXM1 overexpression suppresses their transcription and causes elevated activity of tumor-promoting CDK2 and CDK4/6." (PMID 37686402, 2023). "Stem cell markers, such as NANOG, OCT3/4 and GDF3, contribute to the maintenance of tumor cell pluripotency, and genes involved in proliferation and cell cycle control, including KI67 and CDK4, promote tumor growth." (PMID 37174085, 2023). "In recent years, researchers found that Cdk4/6 inhibitors not only inhibit cell proliferation, but also trigger anti-tumor immune responses." (PMID 37833461, 2023). "The overexpression of CDK4 induces an oncogenic transition of neural progenitor cells into drivers of tumor growth and progression." (PMID 37849813, 2023). "Combining immune checkpoint and CDK4/6 inhibitors synergistically delays tumor growth, providing a rationale for combination strategies comprising CDK4/6 inhibitors and immunotherapies." (PMID 36635767, 2023). "CDK4/6 inhibitors are cyclin-dependent kinase inhibitors that prevent tumor cells from entering the S phase from the G1 phase by acting on the cyclin-CDK4/6 complex, thereby inhibiting tumor growth." (PMID 37483519, 2023). "Then, we detected the protein expression of PHF6 and CDK4 in tumours from mice implanted with PHF6 KD or control HEC‐1‐A cells." (PMID 36756714, 2023). "Owing to their role in tumor biology, CDK4/6 has been considered as a promising molecular target to pharmacologically activate the RB pathway in different cancer types." (PMID 37816718, 2023). "The tumor showed EGFR C797S, T790M, exon 19 deletion (T751_I759>N), CDK4 amplification, MDM2 amplification, CDKN2A/B loss, MTAP loss, low MSI, low TMB and negative PD-L1." (PMID 38111812, 2023). "In several immunocompetent preclinical animal studies, combining CDK4/6 inhibitors and immune checkpoint inhibitors promoted tumour regression." (PMID 36768557, 2023).
tumor (continued). "When given daily, the CDK4/6 inhibitor palbociclib significantly impedes tumour growth in murine models of both estrogen receptor positive and triple negative bone metastatic BC." (PMID 37190140, 2023). "Immune infiltration in TME, including CD8+ T lymphocytes and B-cells, is further enhanced by applying CDK4/6 inhibitors to tumor cells." (PMID 37305685, 2023). "To segregate the effect of CDK4/6 inhibition on tumor cells versus T cells, we performed ex-vivo co-culturing experiments." (PMID 36871040, 2023). "The widespread use of these compounds in preclinical research and clinical trials has provided compelling evidence that CDK4/6i affect several cellular characteristics across different cell types like tumor, immune and stromal cells." (PMID 37835528, 2023). "Upon KRAS activation, cyclin D/CDK4/6 complex get activated, and subsequently phosphorylates retinoblastoma (RB) and promotes tumor cells’ entry into S phase." (PMID 37221195, 2023). "In summary, CDK4/6 inhibitors decrease Treg proliferation but increase tumor infiltration and activation of cyctotoxic T cells leading to an overall enhanced anti-tumor immunity." (PMID 38040730, 2023). "Specifically, PAM50 Luminal A and proliferation signatures were found significantly decreased and increased, respectively, in tumor tissue progressing to endocrine therapy and CDK4/6 inhibition." (PMID 36859416, 2023). "Since cell division is coordinated with the cellular metabolic state, a possible effect of CDK4/6i in tumor metabolism also started to emerge." (PMID 37835528, 2023). "Tumours profiled upon progression following CDK4/6 and aromatase inhibitor treatment are enriched in alterations of the PI3K-AKT pathway." (PMID 37543694, 2023). "A phase 1/2 study looking at dual CDK2 and CDK4/6 inhibitor after progression on CDK4/6 inhibitors in multiple tumor types is also ongoing and addresses a key resistance mechanism to these agents." (PMID 37046675, 2023). "We previously found that CDK4/6 inhibitor monotherapy had excellent anti-tumor effects against de novo MPNSTs in mice, but drug resistance occurred rapidly." (PMID 37686402, 2023). "Preclinical studies suggested that anti-PDL1 therapy promoted synergistic tumor regression in combination with CDK4/6i; however, clinical data with this combination have shown an untenable side effect profile or haves not been statistically significant." (PMID 36980743, 2023). "A combination of SCR-6852 and CDK4/CDK6 inhibitors revealed synergistically anti-tumor activities both in vitro and in vivo." (PMID 37580832, 2023). "We previously showed that exposure to CDK4/6 inhibitors at the time of T cell priming decreased activity of Myc and increased persistence of adoptively transferred tumor-specific T cells in mice." (PMID 36688919, 2023). "Combining STX-478 with fulvestrant and/or cyclin-dependent kinase 4/6 inhibitors was well tolerated and provided robust and durable tumor regression in ER+HER2− xenograft tumor models." (PMID 37623743, 2023). "The p16 gene product plays a relevant role in tumor suppression by inhibiting the key cell cycle-related proteins CDK4/CDK6." (PMID 37132663, 2023). "In the mouse PDA study, CDK4/6 inhibitor treatment reduces tumor volume accompanied by a decrease in pRb and Ki67 as compared to no treatment." (PMID 37591827, 2023). "Targeting cyclin-dependent kinase 4 and 6 (CDK4/6), the proteins controlling cell cycle entry, has become an attractive tumor treatment strategy for RB Transcriptional Corepressor 1 (RB1) wild-type patients." (PMID 37452037, 2023). "After tumor progression to ET + CDK4/6i therapy, patients with HER2-low received a higher number of subsequent lines of systemic therapy (average in HER2-low: 1.47 ± 1.77; average in HER2-0: 1.24 ± 1.49, p < 0.0001)." (PMID 37069173, 2023).
tumor (continued). "Incorporation of a PI3K/AKT/mTOR inhibitor functions synergistically with endocrine therapy and CDK4/6 inhibitors to inhibit tumor growth and prevent or overcome resistance to standard therapy in ER+ metastatic breast cancer." (PMID 36901954, 2023). "CDK4/6i activates tumor cell expression of endogenous retroviral elements, thus, increasing intracellular levels of double-stranded RNA." (PMID 38040730, 2023). "The activation of the CDK4/6 pathway is often observed in various malignancies, driving dysregulated cell cycle and excessive tumor cell proliferation." (PMID 38068930, 2023). "For example, inhibitors of CDK4/6 can block the transition from the G0/G1 phase to the S phase of the cell cycle, thus inhibiting tumor growth, recurrence, and metastasis." (PMID 37274024, 2023). "Some studies reported that CDK4/6i can induce tumor cell metabolic reprogramming and have an impact on mitochondria, lysosomes and glycolysis." (PMID 37835528, 2023). "Incorporating our findings that PIK3CA mutation portends a worse prognosis even when tumor burden is low, patients should consider specific PIK3CA inhibitor in the earliest time after failure of standard first-line treatment of ET plus a CDK4/6 inhibitor." (PMID 37344660, 2023). "In transgenic mouse models, HER2 and CDK4/6i collaborated to inhibit cell proliferation, control tumor growth in vivo, and delay tumor recurrence." (PMID 38293701, 2023). "For patients with a heavy tumor burden, such as bone metastasis and visceral metastasis, it was found that CDK4/6 inhibitors plus ET can still achieve satisfactory therapeutic effects." (PMID 37759823, 2023). "The median tumor volume in St was 2.57 mL (range, 0.23–33.32 mL) before CDK4/6i administration and 3.9 mL (range, 0.121–20.84 mL) after therapy." (PMID 37567880, 2023). "Abemaciclib, a CDK4/6 inhibitor, has shown potential in augmenting tumor-infiltrating T lymphocytes and enhancing T-cell activity in CT26 syngeneic mouse tumors." (PMID 37511431, 2023). "When the cell cycle is intact, it can be targeted by CDK4/6i, so CDK4/6i have become anti-tumor drugs." (PMID 38293701, 2023). "Subsequent to 2010, particularly in recent years, burst keywords encompassed CDK4/6 inhibitors, circulating tumor cells, liquid biopsy, and so forth." (PMID 37692861, 2023). "CDK4/6 inhibitors (CDK4/6i) block the activity of the cyclin D1-CDK4/6 holoenzyme and subsequent dephosphorylation of the Rb tumor suppressor." (PMID 37239834, 2023). "Our results showing frequent loss of p16 expression in the entire tumor or focally (7/9 H3 K27M and 6/8 wt cases) have implications that should be considered more largely, as they may open the path for therapies targeting the p16 pathway (e.g., CDK4 or cyclin D1) in this population." (PMID 36900302, 2023). "Anti-CDK4/6 drugs have been shown to impact different cell types in the tumor microenvironment and enhance tumor immunogenicity." (PMID 37964967, 2023). "CDK4/6 inhibition with anti-PD-1 immunotherapy enhances tumor regression and improves survival rate in a mouse model." (PMID 37298520, 2023). "Enhanced tumor immunogenicity and antitumor immune responses have also been observed with CDK4/6 inhibition." (PMID 37035239, 2023). "These CDK4/6 inhibitors (CDK4/6is) have been shown to inhibit tumor progression, resulting in a better prognosis in combination with ET agents such as AI and FUL." (PMID 37486454, 2023). "As a tumor suppressor, the loss of FAT1 promotes resistance to CDK4/6 inhibitors via the Hippo pathway, which was expressed at low levels in the high-risk group among patients with HER2− BC." (PMID 37529698, 2023). "In present study, we found that HMMR accelerated cell cycle transition and promoted tumour growth via regulating CDK4/6 and p21." (PMID 36750558, 2023). "In another context, Cyclin D binds to cyclin-dependent kinase 4/6 (CDK4/6), facilitating cell entry into the S-phase through the Retinoblastoma-E2F (RB-E2F) pathway and promoting tumor cell proliferation." (PMID 37511431, 2023).
tumor (continued). "CDK4/6i combined with PARPi can inhibit tumor cell proliferation by preventing DNA repair after DNA-damaging agent treatment." (PMID 38037159, 2023). "For example, Palbociclib can halt tumor cell proliferation by inhibiting the G1/S phase transition of the cell cycle, while Ribociclib inhibitors prevent the binding of CDK4/6 to D-type cyclin, thereby blocking the G1/S phase transition." (PMID 38019470, 2023). "RNA-seq analysis of tumor tissues showed increased expression of type I IFNs response genes in tumors developed from Cdk4−/− cancer cells." (PMID 37833461, 2023). "In the next paragraphs, the mechanisms by which CDK4/6 inhibitors can exert their anti-tumor activities beyond simply enforcing cytostatic growth arrest are highlighted, and the primary and achieved resistance to CDK4/6is is discussed." (PMID 37759823, 2023). "Surprisingly, tumour cells treated with CDK4/6 inhibitors exhibit a substantial reduction in DNMT1, which lowers DNA methylation activity of endogenous retroviral genes along with immunoregulatory genes." (PMID 36768557, 2023). "CDK4 was thus resolved by its charge into three main forms as first characterized in thyroid primary cultures and in other tumor types." (PMID 37964967, 2023). "Further, the expression of PD-L1 on tumor cells was significantly enhanced in the palbociclib group, indicating that CDK4/6 inhibitors re-sensitize tumors to anti-PD-1 treatment." (PMID 36871040, 2023). "Even though the induction of senescence contributes to tumor eradication, a durable response to monotherapy of CDK4/6 inhibitors has been shown to be challenging to achieve." (PMID 36765923, 2023). "In our study, the lapatinib + palbociclib combination treatment, targeting the HER2/AKT/mTOR signaling pathway and inhibiting the CDK4/6-Rb bypass pathway, significantly inhibited the survival of tumor cells and induced apoptosis." (PMID 37160904, 2023). "To get an insight into the potential synergistic effect of CDK4/6 inhibition and PD-1 blockade in vivo, we performed IHC and Immunofluorescence (IF) staining in mouse tumor samples." (PMID 36871040, 2023). "The combination of CDK4/6is with immune checkpoint inhibitors is under investigation because of the demonstrated activity of CDK4/6is not only in inducing the tumor cell cycle arrest, but also in promoting anti-tumor immunity." (PMID 37833875, 2023). "As expected, most tumors were scored as luminal A or B. The primary tumor/remote recurrences prior to CDK4/6 therapy start, exhibited a similar frequency of luminal A and B subtypes as observed in the pretreatment metastatic setting." (PMID 37704753, 2023). "Otherwise, concordance was not significantly influenced by the tissue sample type, the time between tumor biopsy and blood draw, or the use of prior CDK4/6i." (PMID 37511178, 2023). "Let-7 has been shown to inhibit the cell cycle regulators cyclin D1, cyclin D3, cyclin A and CDK4 and stop tumour growth." (PMID 38357103, 2023). "Selective CDK4/6 inhibitors have also been reported to not only modulate the cell cycle of tumor cells to induce their arrest, but also to facilitate anti‐tumor immune responses." (PMID 36457244, 2023). "Some studies are combining CDK4/6 inhibitors with AR modulators, the logic behind this being that when ER is positive, AR activation seems to develop tumor suppression activity." (PMID 38067367, 2023). "p16INK4A acts as a tumor- suppressor by binding to CDK4/6 and thus restrict the cell cycle to enter the G1/S phase by cutting off interaction of CDK4/6 and cyclin D1, and later phosphorylation process of retinoblastoma protein (RB1)." (PMID 36961395, 2023).